PRR18 (proline rich 18)
Synonyms: MGC35308
Tractability: No criterion of Open Targets' tractability assessment is met for any kind of drug.
Gene: Protein-coding gene on chromosome 6 (166,305,300 to 166,308,448, reverse strand). Ensembl gene ENSG00000176381.
Genetic constraint (gnomAD): Loss-of-function variants: 0 observed, 0.13 expected, observed/expected ratio (o/e) 0, 90% interval 0 to 1.89. That is too few expected variants to judge how well the gene tolerates losing a copy. Missense variants: 517 observed, 286.21 expected, observed/expected ratio (o/e) 1.81, 90% interval 1.68 to 1.93. Synonymous variants: 228 observed, 134.88 expected, observed/expected ratio (o/e) 1.69, 90% interval 1.52 to 1.88.
Homologues: Orthologues: chimpanzee PRR18 (99% identical), macaque PRR18 (88% identical), rat Prr18 (57% identical), mouse Prr18 (57% identical), tropical clawed frog PRR18 (28% identical), zebrafish prr18 (27% identical), Drosophila melanogaster Rtnl1 (10% identical), Drosophila melanogaster Rtnl2 (4% identical). Paralogues in human: RTN1 (13% identical), RTN4 (12% identical), RTN2 (11% identical), RTN3 (9% identical).